IL1B (interleukin 1 beta)
Diseases named in the same sentence as IL1B in open-access papers (continued):
Sharing a sentence is not in itself a finding about the gene and the disease.
Arthritis (continued). "IL-1β induces inflammation, mitochondrial dysfunction and chondrocyte degeneration, while Sirt3 in arthritis treatment can ameliorate arthritis severity and joint damage through inhibition of the PI3K/Akt/mTOR pathway." (PMID 38913046, 2024). "In vivo experiments confirmed the favorable effects of quercetin in CIA rats, including an improved arthritis score and reduced ankle bone destruction, in addition to a decrease in the pro-inflammatory cytokines IL-1β, IL-6, IL-17, and TNF-α in serum." (PMID 39390367, 2024). "IL‐1β can induce the generation of extracellular matrix‐degrading enzyme and chemokines, leading to arthritis and cartilage and bone destruction." (PMID 38520211, 2024). "After inducing IL-1β-induced arthritis in mice, the Orm2 mRNA expression level increased up to 65.3-fold and 3.2-fold in the liver and affected joints, respectively, as determined by qPCR." (PMID 38556552, 2024). "PMB diminished the arthritis score, cell swelling, and IL-1β and IL-6 secretion in paws as well as combined CAIA model of A. actinomycetemcomitans infection." (PMID 39143049, 2024). "Since it triggers an inflammatory response and encourages the activation and proliferation of inflammatory cells in joints, IL‐1β plays a crucial role in the onset of arthritis." (PMID 39479687, 2024). "The inhibition of Hh signaling in rats with arthritis using cyclopamine, another inhibitor of Shh, reduced the expression of TNFα, IL-1β, and IL-6." (PMID 38668020, 2024). "Conversely, the induction of arthritis in mice (model group) resulted in a significant increase in the levels of IL‐6, IL‐1β, and TNF‐α cytokines in the ankle joint tissue (p < .05)." (PMID 39554315, 2024). "Here, we identified that Saa1, Saa2, and Saa3 expression in the liver, an extraarticular organ, were markedly increased in IL-1β–induced arthritis." (PMID 38426494, 2024). "First, we observed ORM2-induced exacerbation of IL-1β-induced arthritis over a relatively short period of 7 days." (PMID 38556552, 2024). "First, we observed SAA-induced exacerbation of IL-1β–induced arthritis over a relatively short 7-day period." (PMID 38426494, 2024). "In AIA mice, IDM-MMs-loaded DMNs significantly reduced arthritis severity, including paw edema, arthritis index, spleen hyperplasia, and serum levels of IL-1β and TNF-α." (PMID 39771485, 2024). "Considering that MSU-induced arthritis increases total peroxidaseand IL-1β and IL-6 levels, theseinflammatory markers were quantified at the end point of paw edemameasurement." (PMID 38991154, 2024). "plant can also reduce paw and inflammatory swelling, the arthritis index, and TNF-α and IL-1β and increase the production of serum IL-10 in Freund’s complete adjuvant-induced arthritis model in rats." (PMID 38794160, 2024). "Compared to the RA group, the arthritis score of both hUCMSCs and IL-1β stimulated hUCMSCs administration groups were significantly decreased." (PMID 37714911, 2023). "Then we used different concentrations of interleukin-1 beta (IL-1β)-induced in vitro model of arthritis, and found that IL-1β can stimulate cells to release nitric oxide." (PMID 37587519, 2023). "Interleukin 1 beta (Il1b) (highly up-regulated in both datasets) had 37 drugs interactions with the majority of the drugs used to treat arthritis and inflammation." (PMID 37684405, 2023). "To further assess the severity of arthritis, we measured the mRNA levels of a variety of pro-inflammatory cytokines and chemokines, including Il18bp, Il18, Il1b, Il6, Il1r2, Ifng, Cxcl9, Cxcl1, and Cxcl2 in arthritic joints of IL-18BP KO and WT littermates." (PMID 37415987, 2023). "It is reasonable to suspect that local IL-1β release in arthritis plays an integral role in attracting additional inflammatory cells and platelets." (PMID 37500179, 2023).
Arthritis (continued). "Consistent with all of our previous findings, the arthritis control group revealed a significant increase in serum levels of IL-1β, TNF-α, and IL-17 and a significant reduction in the levels of IL-4 in arthritic rats." (PMID 37259429, 2023). "We show that LXA4 reduced TNF-α, IL-1β, and IL-6 levels and increased IL-10 levels in TiO2-induced arthritis." (PMID 37388729, 2023). "MMPs such as MMP2, MMP3, and MMP9 are up-regulated in arthritis, leading to damage to bones and cartilage of joints via activation of IL1β, TNFα, and many other cytokines." (PMID 37765197, 2023). "ELISA detection showed that three doses of WFR can alleviate arthritis in CIA rats in a dose-dependent manner by downregulating abnormally elevated levels of IL-1β, IL-6, and TNF-α (p < 0.01)." (PMID 38098062, 2023). "Our findings suggest that ARHGAP25 has a key role in the pathomechanism of autoantibody-induced arthritis in which it regulates inflammation via the I-κB/NF-κB/IL-1β axis with the involvement of both immune cells and fibroblast-like synoviocytes." (PMID 37234175, 2023). "When arthritic rats were given Nano ZT/Vit B12, their serum levels of RF, CRP, TNF- α, IL-1β, and IL-17 decreased significantly (p ˂ 0.05) when compared to the arthritis group." (PMID 37259429, 2023). "In the LPS-induced acute lung injury model and complete Freund’s adjuvant-induced joint inflammation model, H-PGDS deficiency increased the levels of inflammatory cytokines, including TNFα, IL-1β, and SDF1α." (PMID 37666361, 2023). "Green tea extract can inhibit the expression of IL-1β-induced chemokines This was studied in an experiment with rats having arthritis." (PMID 37893571, 2023). "The combined effect of S100A8, TNF‐α, IL‐1β and IL‐17 induced activated matrix metalloproteinases and exacerbated arthritis." (PMID 37132178, 2023). "The administration of PKRA7, a PKR antagonist, suppressed the severity of arthritis and reduced IL-1β and lL-6 expression in the joint." (PMID 37759478, 2023). "Inhibition of S1P led to decreased serum levels of pro-inflammatory TNF-α, IL-1β, and IL-6 and reduced arthritis activity in previous in vivo experiments, allowing the assumption that S1P is a key regulator of TNF-α stimulated IL-1β and IL-6 release in RA." (PMID 35036874, 2022). "Regarding inflammation, IL-1β was undetectable; nevertheless, IL-1β plays a crucial role in driving the transition from the acute phase of arthritis to the irreversible chronic phase." (PMID 36556927, 2022). "Significant increase in ceramide and decrease in lysophosphatidylcholine were observed in CIA rats, and were highly correlated with arthritis score and IL-1β level." (PMID 36105231, 2022). "Collagen-induced arthritis model rats were randomly treated with IL-1β/TNF-α siRNA, BMSCs and IL-1β/TNF-α siRNA + BMSCs for 28 days." (PMID 36288143, 2022). "In the collagen II-induced arthritis mouse model, the link between [Ca2+]ex and disease activity was confirmed, since the [Ca2+]ex-induced IL-1β response of mouse monocyte correlated closely with the arthritis score." (PMID 36685206, 2022). "For example, high levels of IL-18 and IL-1β are detected in systemic disease; high levels of IL-6 and TNFα, in arthritis; and high levels of IL-1β and IL-6, in fever and skin rash, respectively." (PMID 36090971, 2022). "Arthritis induction led to high levels of IL-1β, CXCL1 (chemokine (C–X–C motif) ligand 1), IL-6, TNF-α, and VEGF, which were markedly decreased after BPI treatment three-, two-, two-, 15-, and threefold, respectively." (PMID 36361854, 2022). "Glucosamine is a nutritional supplement and a natural component of the cartilage that can be used to treat diseases, such as cerebral infarction and arthritis, and exerts anti-inflammatory effects by inhibiting IL-1β." (PMID 36420258, 2022). "To address how IRAK1 signaling affects articular expression of IL-1β, we sought to identify the IL-1β–producing cell types during the early phase of arthritis." (PMID 35801586, 2022).
Arthritis (continued). "For example, in the CIA mouse model and RA patients, the HDAC6 selective inhibitor, CKD-L, inhibits IL-6, TNF-α, and IL-1β expression, and increases IL-10 production, resulting in a decreased arthritis score and inhibited proliferation of effector T cells." (PMID 35453416, 2022). "We used a mouse model of adjuvant-induced arthritis, and at early time-points of the experiment, levels of “classical” pro-inflammatory cytokines, such as IL-1β, IL-6, and TNF, were measured." (PMID 36293292, 2022). "In contrast, IL-1β+ pro-inflammatory monocytes were expanded in rheumatoid arthritis synovia, whereas CD14hi CD16hi neutrophils were expanded in arthritis-irAE." (PMID 35413951, 2022). "Previous studies have shown that ellagic acid alleviated the adjuvant-induced arthritis model in mice by modulation of pro-and anti-inflammatory cytokines (IL-1β, TNF-α, IL-17, IL-10, and IFN-γ)." (PMID 35130279, 2022). "In a rat model of arthritis induced by type II collagen and treated with DAPs, IL-1β, IL-2, IL-6, TNF-α, IFN-γ, and dihydroorotate dehydrogenase (DHO-DHase) were inhibited." (PMID 36235835, 2022). "However, in other IL-1β-driven inflammatory models, such as K/BxN serum transfer-induced arthritis and gout-associated uric acid crystal-induced peritonitis, GSDMD does not drive disease severity, which may reflect inflammasome-independent IL-1β activation and cell death." (PMID 35608339, 2022). "In the study, we found there was a significant positive correlation between IL-1β and arthritis score, which can reflect the severity of joint swelling." (PMID 36105231, 2022). "In the effector phase of human RA and in murine arthritis, IL-1β production by monocytes/macrophages contributes to disease pathogenesis due to chondrocyte activation and cartilage damage." (PMID 36505403, 2022). "In A20-deficient macrophages, MLKL facilitates the LPS-induced release of IL-1β, and in vivo experiments indicate that necroptosis plays an important role in inflammasome-dependent arthritis." (PMID 36522335, 2022). "IL-1β blockade significantly reduced arthritis severity in an antigen-induced arthritis (AIA) mouse model, while Nlrp3 or Nlrc4 gene deletion did not affect AIA." (PMID 35567665, 2022). "Imperatorin is used to treat arthritis as it reduces the levels of interleukin (IL)-1β, IL-6, and tumor cell necrosis factor-α inflammatory factors." (PMID 36435778, 2022). "IL1B plays crucial role in the progression of arthritis via modulation of NF-κB-mediated ERK/STAT signalling pathway while its inhibition decrease inflammation and facilitate the treatment of disease." (PMID 36071528, 2022). "Type 1 immunity protects from pathogens and develops arthritis by the pro-inflammatory effect of IL-1β and IFNγ." (PMID 35163028, 2022). "In particular, IL-6, TNF-α, IL-1β, and IL-8 play a key role in the pathogenesis and development of arthritis, and high levels of these cytokines have been detected in both the serum and the SF of RA, gout, and CPPD patients." (PMID 36361854, 2022). "Compelling evidence has described that NLRP3 inflammasome, and in turn IL-1β secretion, are highly activated in both RA patients and arthritis preclinical models in several type of RA cells (macrophages or monocytes, CD4+T cells, Th17 and synoviocytes)." (PMID 35740048, 2022). "IL-1β leads to activation of the inflammatory cascade in arthritis so chondrocytes treated with IL-1β are used as an in-vitro disease model." (PMID 36506587, 2022). "Joint swelling and the arthritis-related expression levels of IL-1β, IL-6, RANKL, MMP9, and OC-Stamp were strongly reduced, while Foxp3 was induced." (PMID 36003376, 2022). "Arthritis is an autoimmune disease characterized by chronic, low-grade inflammation, accompanied by increased inflammatory cytokines (i.e., IL-1β, TNF-α, and IL-6)." (PMID 35280697, 2022).
Arthritis (continued). "Clinical arthritis scores and the expression levels of proinflammatory cytokines (e.g., IL-17, IL-1β, IL-6, and TNF-α) were significantly attenuated in p40-EBI3-overexpressing and p40-EBI3-Fc-treated mice with CIA compared to vehicle-treated mice with CIA." (PMID 34782759, 2022). "It was previously found that tetrandrine inhibited TNF-α and IL-1β in FCA-induced arthritis at a concentration of 20 mg/kg." (PMID 35222675, 2022). "T cell trafficking and proinflammatory cytokines such as TNF-α, IL-1β, IL-6, and MMPs are reduced when IL-7 is blocked, which lowers joint inflammation." (PMID 35368757, 2022). "Expression of NLRP3, caspase-1, and IL-1 is increased in the synovial tissues of CIA mice, and IL-1α, IL-1β, and IL-1αβ-deficient mice are less sensitive to CIA-induced arthritis." (PMID 35628185, 2022). "The release of pro-inflammatory cytokines such as TNF-α, IL-1β, IL-33, and the process of NETosis are widely known to aggravate arthritis disease status and pain." (PMID 34539449, 2021). "Consistent with the observed clinical and histopathological arthritis phenotype, we found increased expression levels of Tnf, Il1b and the IL-23 target genes Il17a and Il22 in the joints of IL-23 EEV injected mice." (PMID 33983951, 2021). "Levels of the alarmin S100A8/A9 and interleukin (IL)-1β are both increased in arthritis patients and correlate with disease activity and progression of tissue erosion." (PMID 34412663, 2021). "HMW-HA reduced inflammation in experimental arthritis and in interleukin (IL)-1β-stimulated synovial fibroblasts." (PMID 34769349, 2021). "In a mouse model of arthritis Pglyrp2 KO mice were partly protected against arthritis, and WT mice had higher levels of Il1b, Il6, and Tnf-α in the foot and a higher incidence of arthritis." (PMID 33833993, 2021). "Deletion of the Sucnr1 gene led to a reduction in synovial IL-1β levels and significantly reduced knee swelling in an antigen-induced arthritis model." (PMID 33995417, 2021). "ACRH was previously shown to inhibit TNF-α and IL-1β, as demonstrated in adjuvant-induced arthritis in rat." (PMID 34172047, 2021). "Another preclinical study showed that intragastric administration of L. casei prevented the development of Salmonella enterocolitis-induced arthritis and reduced expression of proinflammatory cytokines (e.g., IL-1β, IL-6, IL-17, IL-23, and TNF-α)." (PMID 34065638, 2021). "In corroboration, the administration of PD1 antagonist (MK0524) augments arthritis incidence and severity, increases levels of IL-1β, CXCL-1, and PGE2, whereas reduces the levels of IL-10." (PMID 34539449, 2021). "Several cytokines are responsible for arthritis, such as IL-1b, TNF-α, IL-1β, IL-6 and IFN-γ of dendritic cells, T cells and macrophages, respectively." (PMID 34959384, 2021). "High levels of both the alarmin S100A8/A9 and the pro-inflammatory cytokine IL-1β are found in many patients suffering from various forms of arthritis." (PMID 34412663, 2021). "Numerous commercially available arthritis therapeutics target inflammatory cytokines, including IL-1β." (PMID 34560673, 2021). "Principal component analysis revealed that cells from inflamed tissues polarized in two directions, one for acute IL-1β-induced inflammation (lung or peritoneum) and the other for subacute K/BxN arthritis." (PMID 34001893, 2021). "Neutrophils elicited over 3 h by instillation of IL-1β into lung and peritoneum were much more similar to each other than to those accumulating by day 7 of arthritis." (PMID 34001893, 2021). "It has been shown in a mouse model of arthritis that ER stress provokes inflammation via expression of the ER stress sensor IRE1α that is required for IL-1β activity." (PMID 33247195, 2020). "The primary cytokines required for inducing arthritis in autoimmune models are IL-1β, IL-6, IL-17A, TNF, GM-CSF, and RANKL." (PMID 32792961, 2020).
Arthritis (continued). "The [Ca2+]ex-induced release of IL-1β correlated with both the amounts of [Ca2+] determined in the bone marrow flushes and the severity of arthritis as determined by the CIA score." (PMID 32843625, 2020). "The inflammatory parameters of the TTP deficiency syndrome (weight gain deficits and arthritis) were in general only slightly less pronounced in Il1a−/−TTP−/− and Il1b−/−TTP−/− mice as compared to TTP−/− animals." (PMID 32733464, 2020). "In this study, by using carrageenan/kaolin (C/K)-induced rat models and FLS from arthritis patients that were stimulated with IL-1β, the effects of JC3 dimer on the inhibition of arthritis were evaluated." (PMID 32707885, 2020). "In a type II collagen-induced arthritis rat model, MT exerted its anti-arthritis effects via down-regulation of pro-inflammatory cytokines and proteins (IL-6, IL-8, IL-1β, IL-17A, and TNF-α) and down-regulation of NF-κB." (PMID 33041782, 2020). "In this study, the concentration of CTX‐II and IL‐1β had much higher levels in both the clinical arthritis patients and the experimental KOA rabbit model." (PMID 31840428, 2020). "Inflammatory mediators in arthritis, such as prostaglandin IL-1β, IL-6, and TNF-alpha, directly affect the lymphatic function and reduce the frequency of lymphatic pumps." (PMID 32280355, 2020). "A high level of IL-1 receptor type 16 was observed in osteoarthritic chondrocytes, compared to normal chondrocytes, and inhibitors of IL-1 converting enzyme, a protease crucial for IL-1β processing, was found to reduce collagen-induced arthritis." (PMID 32668590, 2020). "We saw an arthritis-associated inflammation in case of static isotropic tensile strain, as the proinflammatory markers (TNF-α, IL-1β, IL-6, COX-2) were significantly upregulated." (PMID 32485947, 2020). "In a large sample of rats, plasma levels of IL-1β was clearly elevated during the course of arthritis when compared to control animals." (PMID 33051554, 2020). "Scorpion improves collagen-induced arthritis by reducing inflammatory response, via downregulating Tnf and IL-1b in rats." (PMID 32016112, 2020). "HMGB1 can induce the release of tumor necrosis factor-α (TNF-α), interleukin-1β (IL-1β), interleukin 1 (IL-1) and interleukin 6 (IL-6) and it controls the initiation and development of inflammation in various experimental arthritis models." (PMID 32709223, 2020). "Antioxidants like quercetin inhibits inflammation in rat models of chronic MSU-induced arthritis by decreasing inflammatory mediators such as IL-1β." (PMID 33568990, 2020). "It has also been observed that the serum levels of several arthritis-associated or inflammation-associated cytokines, such as TNF, IL-1β, IL-6, and monocyte chemoattractant protein-1 (MCP-1), were augmented." (PMID 32958016, 2020). "Earlier studies showed that green tea hampered arthritis progress in a mouse model, hindered the proteoglycan breakdown and release from OA and RA cartilage treated with IL-1β and TNF-α of human cartilage." (PMID 32668590, 2020). "ELISA and qRT-PCR analysis showed that the induction of arthritis caused a significant increase in the levels of TNF-α, IL-1β, and IL-6 compared to the healthy group." (PMID 32401927, 2020). "In the process of arthritis cartilage destruction, IL-1β can upregulate the expression of Wnt5a which can upregulate the expression of matrix metalloproteinase through the mediation of JNK signaling pathway." (PMID 32299482, 2020). "Nrf2 has antioxidant and anti-inflammatory activity, and its deficiency not only accelerates the progress of arthritis and joint destruction but also promotes the production of TNF-α, IL-1β, and IL-630." (PMID 32071294, 2020). "The 70 % mark of arthritis incidence was reached at 9 weeks of age in Il1b−/−TTP−/− mice and at 15 weeks of age in Il1a−/−TTP−/− mice." (PMID 32733464, 2020). "Previous studies revealed that inhibiting IL‐1β prior to inducing arthritis prevents joint destruction." (PMID 33204425, 2020).